HMOX1 (heme oxygenase 1)
Diseases named in the same sentence as HMOX1 in open-access papers (continued):
Sharing a sentence is not in itself a finding about the gene and the disease.
melanoma (continued). "In vivo studies revealed that ART directly targeted Ido1 in B16F10 cells, decreased Hic1 levels, promoted Hmox1 transcription, facilitated ROS production and lipid peroxidation, aa and induced ferroptosis in melanoma cells, leading to cell proliferation inhibition in melanoma." (PMID 41160271, 2025). "HMOX1 has been shown to be associated with nonmuscle invasive bladder cancer recurrence, cisplatin resistance in muscle invasive bladder cancers, and microenvironment remodeling in melanomas." (PMID 37545464, 2024). "MAP3K5, LURAP1L, HMOX1 might serve as negative risk factor for prognosis of osteosarcoma or melanoma." (PMID 36899330, 2023). "Moreover, ERU increased the expression of antioxidant target genes, such as GCLC, GCLM and HMOX-1, suggesting that the modulation of ROS production and the impairment of mitochondrial activity in the melanoma cells were among the contributing factors, which supported the antitumor activity of ERU." (PMID 36670903, 2022). "Clinically, melanoma patients exhibiting elevated necroptosis-related signatures, such as JUN and HMOX1 expression, show improved responses to ICB therapy and prolonged progression-free survival." (PMID 41235238, 2025). "Through HMOX-1 gene silencing, we were able to demonstrate that the cytostatic activity elicited by HPF in melanoma cells can be partially mediated by HO-1 overexpression." (PMID 37507910, 2023). "We previously showed that mutant BRAF drives the overexpression of HMOX1, which, in turn, forces the nuclear localization of mutant BRAF and drives proliferation and metastasis in melanomas via reactivation or persistent activation of MAPK signaling." (PMID 37176114, 2023). "Immunohistochemistry was applied to evaluate the levels of HMOX-1 and nuclear BRAFV600E expression in melanoma and adjacent healthy tissues." (PMID 35053476, 2022). "The relative expression level of the hub genes was reverified in melanoma cell lines, and showed that HIF1A, IL1B, HMOX1, MMP3, CDKN2A and TIMP1 were upregulated, while PTEN, PRKCA, ATF3 and BRAF were downregulated in melanoma samples." (PMID 36226170, 2022). "In vitro and in vivo results illustrate that nuclear BRAFV600E promotes HMOX-1 overexpression, whereas HMOX-1 reduction represses melanoma cell proliferation and tumor growth." (PMID 35053476, 2022). "Auranofin pretreatment also induced robust activation of the Nrf2 target genes, most pronounced for HMOX1, in TIL from three melanoma patients, KADA, ANRU and BEHA." (PMID 35738800, 2022). "Consistent with previous reports that associated the Nrf2 pathway with SFN-induced chemoprevention, we found that the Nrf2 target genes HMOX1, TXNRD1, GCLC, GCLM, AKR1B10 and G6PD were upregulated after melanoma treatment." (PMID 28864908, 2018). "One such approach involves the use of the antiarrhythmic drug propafenone, which sensitizes melanoma cells to necroptosis by activating the JNK/JUN signaling pathway, upregulating mitochondrial heme oxygenase 1 (HMOX1), and inducing iron overload and ROS accumulation." (PMID 41235238, 2025). "Given the crucial role played by HMOX1 in ferroptosis and the displayed gene upregulation upon CINN-EO treatment, we wanted to ascertain the importance of the HMOX1 protein in the anti-proliferative effect observed in treated melanoma cells." (PMID 36982774, 2023). "Importantly, a Kaplan–Meier analysis revealed lower survival in melanoma patients characterized by high HMOX1 levels (different cut-off values), regardless of the monocyte subtype." (PMID 41109135, 2025). "Furthermore, we utilized a combination of functional enrichment- and gene expression-derived scores to model and identify pathways, such as HMOX1-mediated mitochondrial stress response, as potential key drivers of the emergence of a BRAF/MEK inhibitor-resistant state in melanoma cells." (PMID 37176114, 2023).
melanoma (continued). "As a CD mediated increase in the amount of reactive oxygen species (ROS) and in the amount of Nrf2 activated heme oxygenase-1 (HO-1) was discussed in several publications, the ROS level and HO-1 expression was checked in melanoma cells and non-transformed cells." (PMID 31553748, 2019). "To further elucidate the connection between Hif1α and Hmox1, we subjected MLO-Y4 cells to Hif1α overexpression or an empty vector, followed by exposure to melanoma-derived CM or no treatment." (PMID 39814705, 2025). "The expression of HMOX1, which was present after CINN-EO and TAM+CINN-EO treatment, was absent in untreated and TAM-treated M14 melanoma cells." (PMID 36982774, 2023).
lung carcinoma (106 papers, 2008 to 2026). "Analogously, NRF2 knockdown reduced angiogenesis, concordant with tumor growth reduction, in xenograft models, while NRF2 activation in lung cancer stabilized BACH1 by inducing heme oxygenase 1 (HO1)." (PMID 40507333, 2025). "Immunofluorescence analysis demonstrated that all four active compounds isolated from C. nitidissima leaves were capable of upregulating HMOX-1 expression in NCI-H1975 lung cancer cells to varying degrees." (PMID 40573219, 2025). "In a previously reported study of lung cancer cells, the levels of TP protein were increased by overexpressing HO1, the protein encoded by Hmox1, a direct transcriptional target of Nrf2." (PMID 39190624, 2024). "Pharmacological inhibition of HMOX1 using ZnPPIX was able to suppress lung cancer metastasis by inducing Bach1-destabilization in a Fbxo22-dependent manner." (PMID 33809182, 2021). "Activation of NFE2L2 negatively regulates ferroptosis in various cells (including lung cancer cells) by upregulating various target genes, e.g. heme oxygenase 1 (HMOX1), SLC7A11, GPX4, and superoxide dismutase 2 (SOD2)." (PMID 34742351, 2021). "Nrf2 and HMOX1 synergy will induce angiogenesis through the activation of thymidine phosphorylase in lung cancer cells." (PMID 33324555, 2020). "For example, overexpression of HMOX1 in lung cancer cells attenuated the expression of matrix metalloproteinases (MMPs), which enhance the migration of cancer cells." (PMID 31527696, 2019). "Our data highlight a novel feature of SEMA6A, which is that SEMA6A can reduce lung cancer cell migration through the NRF2/HMOX1 axis in a manner dependent on its cytosolic region." (PMID 31527696, 2019). "HMOX1 was reported as a downstream effector of NRF2 in the migration suppression pathway in lung cancer cells." (PMID 31527696, 2019). "The in vitro results showed that among the compounds, 3d performed effectively anti-growth activity by inducing A549 lung cancer cell apoptosis and activating Nrf-2/HO-1 (heme oxygenase-1) pathway." (PMID 28634389, 2017). "Inhibition of heme oxygenase-1 activity by zinc protoporphyrin IX reduced tumor growth of LL/2 lung cancer in C57BL mice." (PMID 19508729, 2009). "This study elucidates the mechanism by which C. nitidissima exerts its anti-lung cancer effects through the induction of ferroptosis and identifies key active components—apigenin, chrysin, and isochlorogenic acids A and C—that target HMOX-1, a critical molecular player in ferroptosis." (PMID 40573219, 2025). "Stimulation of human lung cancer cells with FSH led to downregulation of heme oxygenase-1 (HO-1) expression, a survival molecule for cancer cells, and increased the ability of the lung cancer cells to infiltrate other sites in the body, suggesting a role in metastasis." (PMID 41463203, 2025). "This study aimed to construct an integrated research system of “natural product extraction-purification, bioactivity evaluation, and computational drug screening” to explore the bioactive compounds in C. nitidissima leaves targeting HMOX-1-mediated ferroptosis and their anti-lung cancer mechanisms." (PMID 40573219, 2025). "In addition, GEPIA2 database showed that KDM1A expression was negatively correlated with HMOX1 expression in lung cancer." (PMID 36357457, 2022). "Nrf2 was shown to suppress the Fbxo22-mediated degradation of Bach1 in a heme oxygenase-1 dependent manner, suggesting that inhibition of heme oxygenase-1 could be an effective therapeutic strategy for preventing lung cancer metastasis." (PMID 34631760, 2021). "Inhibition of Bach1 target gene, HMOX1, or Bach1-ligase overexpression could reduce Bach1-driven metastasis of lung cancer." (PMID 33809182, 2021). "Villalpando-Rodriguez confirmed combined use of siramesine and lapatinib could induce ferroptosis in lung cancer cells by inhibiting heme oxygenase-1 (HO-1) expression." (PMID 34434214, 2021). "NRF2 was reported as an upstream regulator of HMOX1 in another lung cancer cell line, H29220." (PMID 31527696, 2019).
lung carcinoma (continued). "Several studies have expanded the carcinogenic roles of NRF2 and HMOX-1 beyond lung cancer." (PMID 28793787, 2018). "In one study, PG could modulate heme oxygenase-1 (HO-1) activation and decrease lung cancer cell survival." (PMID 29062841, 2017). "In addition, a topologically organized gene network mediated by NRF2 was found to be enriched with genes that were preferentially down-regulated by LAPTM4B knockdown in serum starved lung cancer cells including various anti-oxidant genes (e.g. HMOX1)." (PMID 26343532, 2015). "Together with previous gene expression results, these findings further support the hypothesis that 95% F1 induces ferroptosis in lung cancer cells by activating HMOX-1-mediated pathways, enhancing ROS accumulation, and disrupting intracellular redox and iron homeostasis." (PMID 40573219, 2025). "Treatment of ABC1 and SW900 lung cancer cells, which both contain a functional KEAP1-NRF2 response, resulted in significant induction of NRF2 target gene expression, including NQO1, GCLC, HMOX1 and TXNRD1." (PMID 40890297, 2025). "SEMA6A inhibited the migration ability of lung cancer cells through the NRF2/HMOX1 axis, and SEMA6A overexpression significantly reduced the migration of lung cancer cells." (PMID 41259456, 2025). "qRT-PCR and immunohistochemistry indicated that several key molecules such as Osteopontin/Spp1, Hmox1, Mmp12, and ERBB2 were markedly altered and/or localized in the preneoplastic lesions, suggesting their participation in the induction of lung cancer." (PMID 37513116, 2023). "In lung cancer, the upregulation of BACH1 is mediated by the inhibition of free heme via heme oxygenase-1 (HO-1)." (PMID 37239002, 2023). "In conclusion, the present study identified a novel suppressor of lung cancer cell migration, SEMA6A, which attenuates migration by inducing the NRF2/HMOX1 axis." (PMID 31527696, 2019). "Li and colleagues showed that a low methyltransferase EZH2 expression correlates both lung cancer cell lines and tissues with an elevated expression of NRF2, NQO1 (NAD(P)H-quinone oxidoreductase 1), and HO-1 (heme oxygenase 1)." (PMID 29643973, 2018). "For example, A549 cells, a lung cancer cell line with constitutive NRF2 activation, shows HMOX-1 overexpression relative to other lung cancer cell lines H23, H127, and H460." (PMID 28793787, 2018). "Our study provides new insights into the oncogenic signaling function of LAPTM4B in lung cancer cells and its cross talk with other canonical pathways such as NRF2/HMOX1." (PMID 26343532, 2015). "Similarly, cryptotanshinone (CTS), a bioactive component of Salvia miltiorrhiza, was shown to sensitize gefitinib‐resistant EGFR‐mutant lung cancer cells by targeting catalase (CAT), heme oxygenase 1 (HMOX1) and stearoyl‐CoA desaturase (SCD)." (PMID 37697969, 2023). "Collectively, inhibition of HMOX1 is a feasible anticancer approach, which could account for the activity of CTS in lung cancer." (PMID 35370706, 2022). "In lung carcinoma, NGAL might protect against oxidative stress by activating the nuclear factor E2-related factor 2/heme oxygenase-1 (Nrf2/HO-1) pathway and inducing the expression of heme oxygenase-1 and superoxide dismutase 1,2." (PMID 30231474, 2018). "To better understand the role of GSK-3α and examine the critical genes affected by GSK-3α in lung cancer, we initially screened a subset of NF-κB target genes such as MYC, WT1, BIRC2, IL-9, HMOX1, and TERT, which were regulated by a pan-GSK-3 inhibitor AR-014418 in pancreatic cancer." (PMID 27049759, 2016).
lung carcinoma (continued). "In irradiated A549 lung cancer cells, PGE2, released in the tumor microenvironment, promoted the survival of neighboring non-irradiated cells by enhancing antioxidant defenses through the Nrf2-mediated upregulation of the antioxidant enzyme heme oxygenase-1 (HO-1)." (PMID 40298811, 2025). "For example, HIF-1α could promote ferroptosis by regulating SLC7A11 in hepatic stellate cell or HMOX1 in Leydig and Sertoli cell of testes, and it also was reported to inhibit ferroptosis by activating the Hippo‐YAP signaling pathway in non‐small cell lung cancer or lncRNA-PMAN in gastric cancer." (PMID 37415103, 2023). "Studies have shown HMOX1 has a non-enzyme function to promote chemoresistance in lung cancer." (PMID 33324555, 2020). "The signature works in most cells (but not in all), demonstrating that induction of HMOX1, ZNF469 and HTRA3 is a strong surrogate for BACH1 depletion in lung cancer cells and a good pan-tissue BACH1 signature." (PMID 40716152, 2025).
prostate carcinoma (102 papers, 2007 to 2026). A carcinoma that arises from epithelial cells of the prostate gland. "HMOX1 encodes heme oxygenase-1 (HO-1), which can maintain the stability of prostate cancer cells." (PMID 34722497, 2021). "In addition, KLF14 transactivated HMOX1, which encoded haem oxygenase‐1 and enhanced antioxidant properties of prostate cancer cells." (PMID 34031939, 2021). "The authors postulated that the two-sided regulatory mechanism of BRD4 might prevent prostate cancer cells from a loss of HMOX1 promoting cell survival during oxidative stress." (PMID 31097977, 2019). "To investigate the impact of HMOX1 on prostate cancer cells, we used siRNA to knock down HMOX1. qPCR and Western blotting validated the efficiency of HMOX1 knockdown." (PMID 39850572, 2024). "These experiments demonstrate that TMAO promotes the migration of prostate cancer cells through HMOX1." (PMID 39850572, 2024). "This study provides evidence that S.C effectively suppresses tumor progression and induces ferroptosis in prostate cancer cells by targeting the ROS/USP47/BACH1/HMOX1 axis." (PMID 38195593, 2024). "In the CCK8 assay, co-treatment with TMAO and HMOX1-si-3 showed that si-HMOX1 counteracted the TMAO-induced proliferation of prostate cancer cells." (PMID 39850572, 2024). "Our study found that TMAO enhances the proliferation and migration of prostate cancer cells by upregulating HMOX1 via activation of the MAPK signaling pathway, specifically p38 MAPK." (PMID 39850572, 2024). "In conclusion, TMAO increases HMOX1 expression, promoting prostate cancer proliferation and migration." (PMID 39850572, 2024). "This study provides evidence that S.C effectively suppresses tumor progression and induces ferroptosis in prostate cancer cells by targeting ROS/USP47/BACH1/HMOX1 axis." (PMID 38195593, 2024). "Overall, HMOX1 acts as an oncogene promoting malignant progression in prostate cancer, and its knockdown significantly inhibits cell proliferation and migration." (PMID 39850572, 2024). "In the CCK8 assay, we transfected prostate cancer cells with HMOX1-si-2 and HMOX1-si-3 for 96 h and found that HMOX1 knockdown significantly inhibited cell proliferation." (PMID 39850572, 2024). "In this study, we demonstrated that the gut microbiota-derived metabolite TMAO influences the expression of HMOX1, thereby promoting proliferation and migration of prostate cancer cells." (PMID 39850572, 2024). "Hypoxia in prostate cancer (PC) correlates with chemoresistance to Doc-induced apoptosis via Heme Oxygenase-1 (HO-1) modulation, a key enzyme in heme metabolism." (PMID 39091910, 2024). "TMAO promotes the proliferation and migration of prostate cancer cells by activating the p38 pathway and increasing HMOX1 expression." (PMID 39850572, 2024). "This study found that S.C induces ferroptosis by targeting the ROS/USP47/BACH1/HMOX1 axis in prostate cancer cells." (PMID 38195593, 2024). "We found that TMAO activates the p38 pathway to enhance HMOX1 expression, thereby promoting proliferation and migration of prostate cancer cells." (PMID 39850572, 2024). "More specifically, our study revealed that S.C represses tumor progression and induces ferroptosis in prostate cancer cells by targeting the ROS/USP47/BACH1/HMOX1 axis." (PMID 38195593, 2024). "Heme oxygenase 1 (HO-1) is a detoxifying antioxidant microsomal enzyme that regulates inflammation, apoptosis, cell proliferation, and angiogenesis in prostate cancer (PCa)." (PMID 37232742, 2023). "Different combinations of the following keywords were utilized to obtain articles related to the focus of this manuscript: heme oxygenase 1, prostate cancer, pathogenesis, induction, inhibition, inflammation, precancerous, anti-cancerous, and metastasis." (PMID 37232742, 2023). "Of note is that tannin 158 results in apoptosis in the cell line of human prostatic cancer by decreasing antiapoptotic factors including HuR (human antigen R), HO-1 (Heme oxygenase-1) and SIRT1 (silent information regulator)." (PMID 35678663, 2022).